ADCK2 (aarF domain containing kinase 2)
Diseases named in the same sentence as ADCK2 in open-access papers (continued):
Sharing a sentence is not in itself a finding about the gene and the disease.
cancer (5 papers, 2012 to 2025). A tumor composed of atypical neoplastic, often pleomorphic cells that invade other tissues. "ADCK2 depletion suppressed tumor necrosis factor α (TNFα)-induced hypoxia-inducible factor-1 (HIF-1α) stability in cancer cells." (PMID 36439873, 2022). "In the pEpi primary lung epithelial cells, ADCK2 silencing by the same lentiviral shRNA (“ADCK2-sh”) was unable to significantly reduce CCK-8 viability and EdU incorporation, supporting a cancer cell-specific activity by ADCK2 depletion." (PMID 36439873, 2022). "Since ROS production is essential for cancer cell proliferation, survival, and metastatic potential, disruptions in ADCK2 function could alter oxidative stress responses and tumorigenic signaling." (PMID 40565246, 2025). "Understanding these interactions could provide insights into potential therapeutic strategies targeting ADCK2 in cancer treatment." (PMID 40565246, 2025). "Conversely, depletion of ADCK2 largely inhibited TNFα-induced HIF-1α stability in cancer cells." (PMID 36439873, 2022). "Few studies have reported ADCK2's potential function in cancer cells." (PMID 36439873, 2022). "Interestingly, in normal “pEpi” cells, ADCK2-sh treatment failed to significantly increase nuclear TUNEL ratio/apoptosis, again indicating the cancer cell specific effect by ADCK2 depletion." (PMID 36439873, 2022). "The tissue immunofluorescence staining at the junction of cancer and normal tissues of two representative NSCLC patients (Patient-7#/-13#) showed that ADCK2 expression (green fluorescence) in cancer cells was higher than it in epithelial cells (“Epi”, EpCAM labeling, in red fluorescence)." (PMID 36439873, 2022). "Several reports established a connection of ADCK2 to cancer cell proliferation and motility." (PMID 22355351, 2012). "ADCK2 may play a significant role in the development and progression of various human cancers." (PMID 40565246, 2025). "Therefore, it seems that ADCK2 plays different roles in distinct cancer types." (PMID 35205819, 2022). "Based on these results, we proposed that ADCK2 was required for mitochondrial metabolism in NSCLC cells and depletion of ADCK2 resulted in mitochondrial dysfunction, thereby arresting cancer cell growth." (PMID 36439873, 2022). "ADCK2 is believed to mediate its effects through the RELB-dependent NF-κB signaling pathway, which plays a crucial role in inflammatory responses, cell survival, and metabolic adaptation in cancer." (PMID 40565246, 2025). "Furthermore, our results suggest that four of these genes - ADCK2, PRKAR2B, TRIB2 and TRPM7 - seem to regulate HIF-1α accumulation in multiple cancer cell lines." (PMID 22355351, 2012). "We found that expression of ADCK2 and TRIB2 mRNA is regulated by TNFα in U2OS cancer cells." (PMID 22355351, 2012).
tumor (5 papers, 2022 to 2025). "Despite the low mutation frequency, the observed correlation between ADCK2 expression and tumor size underscores the need for further research to elucidate its role in tumorigenesis and its potential as a therapeutic target." (PMID 40565246, 2025). "After these analyses, only an inverse association of tumour size (T1 vs. T2–4) and ADCK2 mRNA expression (p = 0.040) remained statistically significant." (PMID 36085291, 2022). "Nevertheless, the suggested inverse association between ADCK2 mRNA levels and tumour size encourages further investigation into its role in tumour development." (PMID 36085291, 2022). "Given the critical role of these pathways in tumor progression, further research is needed to elucidate the precise molecular mechanisms by which ADCK2 regulates NF-κB signaling, redox homeostasis, and oncogenesis." (PMID 40565246, 2025). "In vivo studies of ADCK2 knockout led to a reduction in cellular proliferation, viability, motility, and cell cycle progression, indicating its role in tumor growth and progression." (PMID 40565246, 2025). "In NSCLC tumor tissues (“T”) ADCK2 mRNA expression was dramatically elevated when compared to its expression in the adjacent normal lung tissues (“N”)." (PMID 36439873, 2022). "This interplay suggests that manipulating ADCK2 levels could offer insights into therapeutic strategies aimed at mitigating tumor spread and enhancing treatment outcomes." (PMID 40565246, 2025). "Suppressing ADCK2 profoundly inhibited NSCLC cell viability, proliferation, and motility, disrupted essential mitochondrial functions, and weakened Akt-mTOR signaling, ultimately curbing tumor growth." (PMID 41213905, 2025).
myopathy (3 papers, 2019 to 2024). A disease of the muscle in which the muscle fibers do not function properly. "We propose that patients with isolated myopathies and myopathies involving lipid accumulation be tested for possible ADCK2 defect as they are likely to be responsive to CoQ supplementation." (PMID 31480808, 2019). "From a clinical point of view, isolated myopathies and myopathies with lipid accumulation should be tested for this ADCK2 gene defect because they are likely to be responsive to CoQ supplementation." (PMID 31480808, 2019).
mitochondrial disease (1 paper, 2022). "ADCK2 haploinsufficiency can be grouped into mitochondrial diseases due to defects in nuclear-encoded genes whose encoded proteins are located inside mitochondria." (PMID 35936917, 2022).
ADCK2 also shares sentences with these, for which no sentence is quoted: prostate carcinoma (3 papers); endometrial carcinoma (1); non-small cell lung carcinoma (1); retinoblastoma (1); uterine carcinosarcoma (1).